APC (APC regulator of Wnt signaling pathway)
Diseases named in the same sentence as APC in open-access papers (continued):
Sharing a sentence is not in itself a finding about the gene and the disease.
colon carcinoma (continued). "TE transposition can cause new mutations, as shown in colon cancers, where LINE1 insertions were found to compromise the function of the tumor suppressor adenomatous polyposis coli (APC)." (PMID 36010577, 2022). "We identified that in APC-wt/MSS colon cancer, the expressions of PD-1, PD-L1, CTLA4, and CYT (GZMA and PRF1) were increased." (PMID 35937946, 2022). "And in June 2021, it was proposed that the tumor suppressor gene APC is involved in the regulation of colon cancer." (PMID 36258178, 2022). "Based on the results, we found that more colon cancers of APC-wt/MSS are classified by TMIT I. And APC-wt/MSS colon cancer patients are more likely to benefit from antitumor immunotherapy." (PMID 35937946, 2022). "The high expression of β-catenin caused by mutations in components of the WNT signaling pathway, such as the APC tumor suppressor, is one of the most frequent and early genetic changes that occur in colon cancer." (PMID 36012568, 2022). "In colon cancer, RSPO2 and RSPO3 gene fusions have been proposed to potentiate Wnt/β‐catenin signaling, providing a mutational alternative for classical APC and CTNNB1 mutations." (PMID 36106661, 2022). "Early reports showed that APC indirectly inhibits PPARβ/δ expression in colon cancer via the suppression of β-catenin/Tcf-4-mediated transcription." (PMID 35954274, 2022). "The results show that APC-wt colon cancer was significantly enriched in 115 KEGG pathways (P < 0.05)." (PMID 35937946, 2022). "Unveiling new therapeutic vulnerabilities, these findings prompted the development of RSPO-targeted therapies for the 10% of APC-proficient colon tumours harbouring RSPO2 and RSPO3 gene fusions." (PMID 33673710, 2021). "In this report, we deduced mechanistic work utilizing APC mutant colon cancer cells and adjacent normal and colon tumor tissue samples from ETBF ApcMin/+ mouse model treated with Anthos." (PMID 34926717, 2021). "While the oral administration of metformin or niclosamide alone was minimally effective compared to the control, their combination significantly suppressed colon tumor progression in the APC-mutant model in terms of the number and area of tumors." (PMID 34298652, 2021). "In vitro work using the APC mutant HT-29 colon cancer cells showed a clear dose-dependent decrease in the phosphorylation status of Src (Y418) and EGFR (Y1068)." (PMID 34926717, 2021). "More importantly, high PLK1 expression significantly improved the survival of patients with colon cancer expressing a truncated APC." (PMID 33996604, 2021). "APC mutations in the Wnt/β-catenin pathway and KRAS mutations, the major form of RAS, are frequently found in colon cancer." (PMID 34203665, 2021). "Previous data suggest early upregulation of SND1 in colon cancer and its potential contribution to early colon carcinogenesis, mainly as a key regulator of colon cancer-development mediators such as β-catenin and APC." (PMID 34809722, 2021). "Over half of the PhIP-induced colon tumors in F344 rats harbored a GC base pair deletion in 5′-GTGGGA-3′ at codon 635 of the APC gene." (PMID 34271992, 2021).
colon carcinoma (continued). "The results show that determining the APC status cannot help for the prediction of metastasis and cannot be used to classify stage II colon cancers." (PMID 33237662, 2021). "This mutation occurred in the tumor suppressor gene adenomatous polyposis coli (APC) in 50% of PhIP-induced colon tumors in rats." (PMID 34271992, 2021). "SRP19 mRNA and protein levels were lowered in cell lines harboring APC deletion and shRNA targeting SRP19 inhibited proliferation of cells, confirming Srp19 as a CYCLOPOS gene in colon cancer with APC loss." (PMID 34113652, 2021). "Adenomatous polyposis coli (APC) is a tumor suppressor protein in colon cancer and an anchor protein that binds to β-catenin with postsynaptic density postsynaptic density (PSD)-93/95 in the adhesion complex of the synaptic membrane." (PMID 34948207, 2021). "Since the sporadic adenoma curve is right shifted compared to the FAP adenoma curve and both are S-shaped, this finding suggests that at least two hits in APC are required for autocatalytic polymerization to increase in colon tumor formation." (PMID 32079164, 2020). "In another colon cancer model, the intestinal infection with the nematode Trichuris muris accelerated the progress of spontaneously developed intestinal adenomas in APC min/+ mice." (PMID 32547942, 2020). "Considering that APC is known for its contribution in the chromosomal instability seen in many colon cancer cells, it seems natural for chromatin regulation to appear as one of the controlling mechanism of the earliest events of cancer development." (PMID 33133158, 2020). "Mutational inactivation of human adenomatous polyposis coli (APC) gene deregulates the Wnt signaling pathway and is a frequent genetic event in colon cancers." (PMID 33202710, 2020). "Even though we demonstrate that C2 can selectively target APC-driven colon cancer growth, subsequent more comprehensive studies will provide a detailed mechanistic rationale for its further optimization." (PMID 32415084, 2020). "APC represses PPARβ/δ expression through inhibition of β-catenin/Tcf-4 regulated transcription in colon cancer cells." (PMID 32375405, 2020). "Curcumin has also been reported to inhibit NF-κB-luciferase HT-29 and in HCT-116 colon cancer cells and to inhibit Wnt/β-catenin pathway in vitro in HCT-116 colon cancer cells and in vivo in mice carrying APC gene mutation." (PMID 33202681, 2020).
colon carcinoma (continued). "The alterations in expression of APC gene lead to changes in expression of APC protein and abnormalities in cell cycle and hence promoting colon cancer." (PMID 32458646, 2020). "In the colon cancer subset (594 samples), APC and CNOT3 were altered in 66.67% and 1.18% of cancers, respectively." (PMID 31231471, 2019). "Mutations in APC or AXIN that impair β-catenin degradation upregulate WNT signaling, leading to hyperproliferation and facilitating colon cancer development." (PMID 31623618, 2019). "MIIP is able to interact with Cdc20 and suppress the activity of APC/CCdc20, thus blocking the degradation of two mitotic check proteins, cyclin B1 and securing, leading to impaired mitotic transition in glioma and colon cancer model." (PMID 31092266, 2019). "Curcumin inhibits Wnt/β catenin pathway by suppressing c-myc expression, induce caspase 3 mediated cleavage of β-catenin, E-cadherin, and APC, which were linked to apoptosis and G2/M phase arrest in HCT-116 colon cancer cells." (PMID 31108984, 2019). "More strikingly, we observed increased frequency of the APC-driven colon tumors in Ppm1dT/+ mice and their reduced survival." (PMID 31659152, 2019). "Majority of tumors in colon cancer comprehend defects in the Adenomatous polyposis coli (APC) gene that results in β-catenin up-regulation and constitutive signaling by the β-catenin- TCF complex." (PMID 31699039, 2019). "Colon cancer is initiated by the inactivation of APC, which leads to the activation of the WNT pathway and the development of colon cancer in a MYC-dependent manner." (PMID 31623618, 2019). "APC plays a vital role in controlling colon cancer cell growth via regulation of gene transcription mediated by β-catenin." (PMID 31108984, 2019). "Kruppel Like Factor 4 (KLF4) is a target of the tumor suppressor gene Adenomatous Polyposis Coli (APC) and its overexpression reduces cell migration and invasion in vitro and tumorigenicity of colon cancer cells in vivo." (PMID 31337362, 2019). "Unexpectedly, we found that deletion of Bcl9/9l accelerated an APC-driven model of intestinal tumorigenesis and favoured adenoma formation within the proximal SI, but suppressed colonic tumour growth." (PMID 30760720, 2019). "Since ~90% of colon cancers are associated with defects in the canonical Wnt signaling pathway, we selected colon cancer cell lines HCT116 and DLD-1 with mutations in APC and CTNNB1, respectively." (PMID 30996256, 2019). "Knockdown (kd) of TMED3 was achieved in CC14 primary human colon cancer cells, which are E1554->frameshift APC mutant, using a previously validated specific short-hairpin RNA (shTMED3 with kd of 95%)." (PMID 31253868, 2019). "Overexpression of β-catenin and APC (adenomatous polyposis coli) genes are seen in colorectal carcinoma, mediating uncontrolled cell proliferation and development of colon cancer." (PMID 29861465, 2018). "These mutational and silencing observations in patients are consistent with PDE4B serving a protective function in the major APC-dependent pathway to frank colon cancer." (PMID 30188895, 2018). "For instance, the KRAS, PTEN and APC genes are well-established tumor drivers in many different tumor types, including colon cancer." (PMID 29621323, 2018). "To explore the functional significance of APC depletion in upregulating the Wnt/β-catenin pathway in colon cancer cell lines, as well as in the activation of β-catenin induced by miR-494, we studied the effects of APC depletion using specific siRNAs." (PMID 29304823, 2018). "The careful comparison of KRAS-dependent and KRAS-independent colon cancers led to the identification of MAP3K7, encoding the TGF-β-activated kinase (TAK1), as a driver of cell survival of KRAS-mutated-dependent, APC-deficient cells." (PMID 29652830, 2018).
colon carcinoma (continued). "Chromatin immunoprecipitation of APC was performed in two biological replicates from HCT-116 colon cancer cells that express wild-type APC but also a degradation-resistant point mutant of β-catenin that constitutively activates canonical WNT signaling." (PMID 30131849, 2018). "Our observations suggest that the expression of APC-ΔC can compromise the SAC in colon cancer with different degrees of chromosomal instability." (PMID 29549256, 2018). "High PLK1 expression increases the survival of colon cancer patients expressing a truncated APC significantly." (PMID 29549256, 2018). "Based on the annotation from ClinVar and COSMIC, rs137854573 in APC has been reported to be a dominant variant causing FAP, and detected in colon cancer and ovarian cancer." (PMID 30619485, 2018). "Here we study the role of PLK1 in colon cancer cells with chromosomal instability promoted by APC truncation (APC-ΔC)." (PMID 29549256, 2018). "Subsequently, tissues were analysed by immunofluorescence: confocal microscopy analysis confirmed the upregulation of IntegriSense probe in neoplastic tissues (APC+/min) compared to healthy mucosa (WT), both in small intestine and colon tumors (respectively)." (PMID 30140377, 2018). "In human colon cancer, the inactivation of the adenomatous polyposis coli (APC) gene is present in the large majority of patients, with concomitant stabilization and accumulation of β-catenin especially in the epithelium [reviewed in Ref." (PMID 29867918, 2018). "Through this direct binding via ARC4/5 domains in the cytosol, Prx II protects TNKS against the oxidative inactivation and preserves the deregulated β-Catenin pathway in APC-mutant colon cancer cells with high endogenous H2O2 expression." (PMID 30177619, 2018). "This study was inspired by an experiment showing that APC+/- mice infected with S. Typhimurium developed colon cancer following infection." (PMID 29342165, 2018). "In adult mice with a dominant mutated APC gene, conditional knockout of TCF4 significantly enhances colon tumor formation, indicating that TCF4 is a tumor suppressor." (PMID 29975781, 2018). "Taken together, in BI6727-treated colon cancer cells the expression of APC-ΔC can reduce the accumulation of cells in mitosis." (PMID 29549256, 2018). "A murine model of the conditional suppression of APC provided clear evidence that APC disruption is required for colon tumor development and maintenance." (PMID 29652830, 2018). "In HT-29 colon cancer cells with inactivated APC, EGCG (20 μM) was shown to lower p16INK methylation after 6 days in cell culture conditions." (PMID 29259973, 2017). "All five of the colon cancer cell lines we tested contain mutations in the Wnt/β-catenin signaling pathway; HT29, LoVo, SW480 and SW1116 have mutations in APC whereas HCT116 contains a mutated version of β-catenin that results in increased protein stability." (PMID 28704539, 2017). "Recently, our laboratory reported that loss of APC predisposed to silencing of FXR via CpG hypermethylation in colonic mucosa of APCMin/+ mice and in HCT-116 human colon cancer cells." (PMID 29259973, 2017). "In genetic mouse models, Smad3 or Smad4 mutation increases malignancy and invasiveness of intestinal tumors in APC min/+ or APC Δ716/+ mice, pointing to a significant role of TGFβ signaling in repressing malignant progression in colon tumors." (PMID 28414818, 2017). "Since gastric and colon tumors share some common genetic lesions, it is relevant to investigate the role of APC tumor suppressor gene in the case of diffuse type gastric cancerwhich is not well characterized." (PMID 28576136, 2017). "Thus, APC deficits linked to colon cancer may influence mitochondrial control of SOCE." (PMID 28903423, 2017). "Previous study showed that truncations in APC eliminate microtubule binding contributing to chromosome instability (the CIN phenotype) in colon cancer cells because they directly affect chromosome-spindle attachment." (PMID 28576136, 2017).
colon carcinoma (continued). "This is consistent with previous findings in which we and others have shown that Wnt pathway activity can still be modulated in colon cancer cells with mutant APC." (PMID 28600348, 2017). "However, high folate consumption also appears to reduce the risk of APC wildtype colon tumors, while being positively associated with APC mutated colon tumors in men, indicating that folate may also enhance colorectal carcinogenesis through a distinct APC mutated pathway." (PMID 29249914, 2017). "We evaluated mice of various Slco2a1 genotypes in a murine model of colon cancer, the adenomatous polyposis (APC) mutant (Apc∆716/+) model." (PMID 29185482, 2017). "Previous studies showed that PPARγ can suppress beta-catenin levels and colon carcinogenesis but only before damage to the APC/beta-catenin pathway, suggesting a potentially important use for PPARγ ligands as chemopreventive agents in colon cancer." (PMID 29221176, 2017). "In nearly all colon cancer tumors, the APC protein is truncated, but still retains partial binding abilities." (PMID 28708837, 2017). "Over-expression of APC in fibroblasts and colon cancer cell lines leads to arrest of G1 phase in the cell cycle." (PMID 28576136, 2017). "Earlier studies have reported that MPC1 is downregulated in colon cancer and its expression positively correlates with APC." (PMID 28397687, 2017). "Fourth, activating mutations in β-catenin or inactivating mutations in APC or Axin have been described in ALL, akin to well-known activating mutations in colon carcinomas." (PMID 27571104, 2016). "To investigate the effect of these mutations on STRAP-induced stabilization of β-catenin, we chose three different human colon cancer cell lines, SW480, HCT116 and RKO having different mutational status in APC and β-catenin genes." (PMID 26910283, 2016). "More relevant to human APC-dependent colon cancers, ApcMin/+:Thbs1−/− mice fed a high-fat diet had a 48% (P<0.02) increase in adenoma formation in the large intestine when compared with ApcMin/+ mice fed the same diet." (PMID 27239962, 2016). "To further confirm that the effect of H2 is on phosphorylation and not ubiquitination of β-catenin, we examined the effect of H2 on HT-29 human colon cancer cells harboring truncated APC." (PMID 27558955, 2016). "Our previous study demonstrated that ARL4C overexpression is detected in colon cancer and lung adenocarcinoma where genetic alterations in APC, β-catenin, and Ras are frequently observed." (PMID 27835592, 2016). "In contrast, STRAP stabilizes β-catenin in colon cancer cell lines with wild type APC and β-catenin." (PMID 26910283, 2016). "For example, LEF-1 over-expression alone is sufficient to induce EMT in a developmental context, but both LEF-1 over-expression and APC truncation are required to induce EMT in a colon cancer setting." (PMID 27196929, 2016). "Mutations in APC and KRAS were frequently co-occurring in this series of 60 MSS colon cancer samples (Fisher-Exact: p = 0.002)." (PMID 27729614, 2016). "For instance, more than 80% of colon cancers bear truncations in APC, resulting in active β-catenin accumulation in the nucleus, the initial stage of transformation." (PMID 26029888, 2015). "The identification of heterozygous germline mutations in familial adenomatous polyposis (FAP) syndrome has highlighted the role of the adenomatous polyposis coli (APC) gene in sporadic tumor development and has clarified mechanisms by which colon tumors arise." (PMID 26186212, 2015). "We further examined the effects of Z86 on endogenous Wnt signaling in colon cancer cell lines, SW480 (with APC deficiency) and HCT116 (harboring mutated β-catenin), in which the Wnt/β-catenin signaling pathway is constitutively activated." (PMID 27551464, 2015).